HOTAIR (HOX transcript antisense RNA)
Diseases named in the same sentence as HOTAIR in open-access papers (continued):
Sharing a sentence is not in itself a finding about the gene and the disease.
bladder cancer (continued). "In the present study, we demonstrate for the first time that overexpression of HOTAIR contributes to cisplatin-induced bladder cancer cachexia." (PMID 36471329, 2022). "Several studies have reported that HOTAIR is the main player in various malignancies including bladder cancer, colon cancer, lung cancer, and breast cancer." (PMID 36685879, 2022). "Cisplatin treatment increased EGFR and NF-κB activation and upregulated ProT and HOTAIR expression in bladder cancer cells." (PMID 36471329, 2022). "In the present study, our results highlight for the first time a critical role for HOTAIR in cisplatin-induced bladder cancer cachexia." (PMID 36471329, 2022). "Our results obtained from cell culture, clinical samples, and animal models elucidate for the first time the pathological role for HOTAIR in cisplatin-induced bladder cancer cachexia." (PMID 36471329, 2022). "Our data obtained from bladder cancer are consistent with previous reports in other cancers showing the involvement of HOTAIR in cisplatin resistance." (PMID 36471329, 2022). "Herein, our in vitro data demonstrate that HOTAIR positively regulates proliferation of bladder cancer cells." (PMID 36471329, 2022). "In conclusion, our animal studies provide evidence to show that HOTAIR is involved in cisplatin-induced bladder cancer cachexia." (PMID 36471329, 2022). "Taken together, these results indicate that forced expression of HOTAIR or ProT in human bladder cancer cells enhances the expression of IL-6, TNF-α, and IL-1β." (PMID 36471329, 2022). "In bladder cancer cells and tissues, HOTAIR, via the recruitment of PRC2 and LSD1, is directly involved in the regulation of miR-205 expression." (PMID 33540611, 2021). "In particular, HOTAIR was shown to mediate recurrence and progression in bladder cancer via the histone methyltransferase EZH2." (PMID 31195674, 2019). "This is strongly supported by our results showing that PI3K inhibitor wortmannin downregulated HOTAIR expression in human bladder cancer cells." (PMID 29190895, 2017). "HOTAIR has been found to be highly expressed in several cancers and related to the recurrence of bladder cancer." (PMID 29190895, 2017). "In this study, we found that the levels of the HOTAIR expression were much higher in bladder tissues and in bladder cancer cells." (PMID 26469956, 2015). "In vitro study with bladder cancer cell lines yielded consistent results with a 20-fold increase of the HOTAIR expression in bladder cancer cell lines when compared with that in normal HCV29 cells." (PMID 26469956, 2015). "To study the contribution of HOTAIR and its potential upstream EGFR-ProT axis to cisplatin-induced bladder cancer cachexia, we first asked whether HOTAIR, ProT, and EGFR were overexpressed in clinical bladder tumor tissues." (PMID 36471329, 2022). "HOTAIR also participated in the resistance to doxorubicin in bladder cancer cells." (PMID 36471329, 2022). "Knockdown of Hotair resulted in an approximately two-fold decrease in the IC50 value of cisplatin in MBT-2 cells, suggesting that HOTAIR may mediate cisplatin resistance in bladder cancer." (PMID 36471329, 2022). "High expression of HOTAIR and GAS5 was shown to be associated with poor survival in bladder cancer." (PMID 36685879, 2022). "In addition, lncRNA HOTAIR was significantly up-regulated in patients with 81.8% T1 and T2 bladder cancer, and the up-regulated lncRNA HOTAIR was closely related to bladder cancer recurrence and cell infiltration." (PMID 34026626, 2021). "In bladder cancer, HOTAIR is a prognostic biomarker involved in chemo sensitivity to doxorubicin." (PMID 33540611, 2021). "Additionally, higher urinary exosomal HOTAIR, MALAT1, PCAT-1, higher plasma exosomal H19, and higher serum exosomal UBC1 in NMIBC were associated with poorer prognosis of bladder cancer patients." (PMID 32517366, 2020).
bladder cancer (continued). "Finally, they used The Cancer Genomic Atlas (TCGA) data set for bladder cancer to show that HOTAIR expression is correlated with stage of UBC with the most invasive T4 tumors having the highest level of HOTAIR expression." (PMID 26800519, 2016). "As the expression of lncRNA HOTAIR was upregulated in bladder cancer, we speculate that HOTAIR could mediate the silencing of miR-205 through its regulation on the histone modification." (PMID 26469956, 2015). "Our findings indicate that HOTAIR expression has prognostic value for bladder cancer progression, recurrence, and survival and suggest that HOTAIR plays active roles in modulating the cancer epigenome, becoming an interesting candidate as a target for cancer diagnosis and therapy." (PMID 26457124, 2015). "Together, these results suggest that, despite not being associated with bladder cancer risk, HOTAIR rs920778 and rs12826786 polymorphisms might represent new prognostic factors in this type of cancer." (PMID 38275875, 2024). "Our retrospective analyses using 106 bladder cancer patients and 199 cancer-free controls demonstrated that, despite not presenting an association with bladder cancer risk, HOTAIR rs920778 TT and rs12826786 CC genotypes are associated with a better prognosis for bladder cancer patients." (PMID 38275875, 2024). "It is particularly interesting to note that while the HOTAIR rs920778 and rs12826786 genetic variants seem not to affect the patient’s susceptibility to developing bladder cancer, they might influence patient outcomes." (PMID 38275875, 2024). "In addition, HOTAIR could serve as a urinary liquid biopsy biomarkers to distinguish bladder cancer from chronic urocystitis." (PMID 34367966, 2021). "In addition, ΔNp63, a likely regulator of stemness in genitourinary epithelia, was differentially expressed indicating that aberrant HOTAIR expression may be involved in the establishment of aberrant differentiation states in bladder cancer." (PMID 25994132, 2015). "However, the understanding on the function of HOTAIR is still scarce in bladder cancer." (PMID 26469956, 2015). "Irregular expression of HOTAIR, UBC1, H19, and GAS5 has been reported to be related to overall survival in bladder cancer however, more confirmative studies are needed to make a definite conclusion." (PMID 36685879, 2022). "Taken together, these results indicate that cisplatin can upregulate the expression of ProT and HOTAIR and that activation of EGFR and NF-κB participates in this pathway in bladder cancer cells." (PMID 36471329, 2022). "In bladder cancer, the HOTAIR/miR-205/CCNJ (cyclin J) axis has been shown to promote growth, whilst HOTAIR silences the tumor suppressive miR-205 by disrupting the balance of histone modifications on the miRNA promoter." (PMID 29702599, 2018). "The analysis of HOTAIR and EZH2 expression in nine different non-invasive bladder cancer cell lines also showed that those cells showing high EZH2 protein levels also displayed high HOTAIR expression, thus reinforcing their co-regulation." (PMID 26457124, 2015). "Here, we report the expression analysis of HOTAIR and ANRIL, which cooperate with PRC2 to allow specific gene repression and their possible roles as prognostic biomarkers in bladder cancer." (PMID 26457124, 2015). "Using overexpression, knockdown, and pharmacological approaches in bladder cancer cell lines, we also observed that EZH2 regulates HOTAIR expression." (PMID 26457124, 2015). "Specifically, HOTAIR is upregulated in bladder cancer samples as compared to non-tumoral tissues, and this high expression is predictive of a shorter overall survival, time-to-recurrence, and disease progression." (PMID 38275875, 2024). "In addition, the inhibition of HOTAIR has been demonstrated to regulate Notch1-mediated EMT pathways in bladder cancer and thereby promoting metastatic properties of bladder cancer." (PMID 36685879, 2022).
bladder cancer (continued). "To further validate that ProT upregulated HOTAIR expression through the NF-κB signaling, we silenced ProT expression in ProT-high-expressing TCCSUP bladder cancer cells via lentivirus-mediated delivery of shRNA specific to ProT, which was confirmed by RT-qPCR and immunoblotting." (PMID 36471329, 2022). "Thus, many HOTAIR effects depend on EZH2, which is strongly upregulated both in breast and bladder cancers." (PMID 25994132, 2015). "We did not observe the recently reported widespread increase of HOTAIR expression in pTa/pT1 bladder cancer tissues, but our cohort is derived from cystectomies and contains few cancers of those stages." (PMID 25994132, 2015). "Moreover, the silencing of miR-205 expression in T24 cells with imbalanced H3K4me3 and H3K4me3 was reversed in T24 cells with knockeddown HOTAIR expression, suggesting a direct role of HOTAIR on the regulation of miR-205 expression via the recruiting PRC2 and LSD1 in bladder cancer." (PMID 26469956, 2015). "A panel of 96 target lncRNAs was used as a probe, some of which have been previously demonstrated to be involved in the development of bladder cancer or other tumors (UCA1, MALAT1, H19, and HOTAIR), while others have not yet been characterized." (PMID 38846969, 2024).
thyroid cancer (27 papers, 2018 to 2025). "Up-regulation of HOTAIR has been found in thyroid cancer and is associated with metastasis and poor prognosis." (PMID 40463874, 2025). "A study based on the TCGA and Gene Expression Omnibus (GEO) showed that HOTAIR was associated with poor survival of thyroid cancer patients." (PMID 29351231, 2018). "For instance, the lncRNA HOTAIR has been implicated in thyroid cancer metastasis." (PMID 38949925, 2024). "However, despite the numerous evidence on the role of HOTAIR as a diagnostic and prognostic marker in the majority of solid tumors, only one clinical trial performed on thyroid cancer patients (ClinicalTrials.gov Identifier: NCT03469544) is ongoing." (PMID 38887279, 2024). "Regarding another investigated lncRNA, HOTAIR is differentially expressed in both tissues and plasma of thyroid cancer (TC) patients compared to controls, with higher levels associated with tumor aggressiveness and progression." (PMID 41150811, 2025). "There is a lack of in-depth information regarding the general role of lncRNAs in thyroid carcinoma since much of the research conducted to date has concentrated almost exclusively on a small group of well-characterized lncRNAs, such as HOTAIR and MALAT1." (PMID 40468332, 2025). "Compelling evidence suggests that aberrantly expressed HOTAIR plays a role in thyroid cancer progression." (PMID 38339237, 2024). "Overexpression of HOTAIR affects survival in vivo in the xenograft tumor model with HTh7 thyroid cancer cells in nude mice." (PMID 38339237, 2024). "HOTAIR promotes proliferation and inhibits apoptosis of thyroid cancer cell lines (HTh-7, CAL-62, BCPAP) by silencing the expression of protein phosphatase methylesterase 1 (PPME1) by miR-761 sponging." (PMID 38339237, 2024). "Using papillary (BCPAP) and anaplastic (HTh-7 and CAL-62) thyroid cancer cells, HOTAIR/miR-761 sponge can regulate PPME1 to promote cell proliferation and inhibit cell apoptosis." (PMID 36494673, 2022). "For examples, using papillary (TPC-1) and follicular (FTC-133) thyroid cancer cell lines, HOTAIR was showed to sponge miR-1, activate CCND2 expression, and promote thyroid cancer progression." (PMID 36494673, 2022). "HOTAIR negatively regulates miR-1 by direct competitive binding to the miR-1 locus and participates in the regulation of thyroid cancer cell carcinogenesis." (PMID 32596158, 2020). "HOTAIR has been found to be significantly upregulated in thyroid carcinoma cells as well as thyroid cancer tissue samples and plasma." (PMID 32596158, 2020). "HOTAIR is upregulated about 80 times in thyroid cancer and promotes metastasis of thyroid carcinoma cells." (PMID 33402862, 2020). "Thyroid cancer cells exhibit upregulated expression of HOTAIR compared to normal thyroid cells." (PMID 40463874, 2025). "Moreover, silencing of the dlx1 gene in thyroid cancer cells occurs due to HOTAIR-dependent recruitment of PRC2 to the promoter and consequent H3K27me3 deposition, which ultimately increases proliferation, colony formation, and migration of cells." (PMID 40149701, 2025). "In particular, HOTAIR has been registered as a biomarker in thyroid cancer." (PMID 39273054, 2024). "Therefore, it is undoubtedly that HOTAIR can sponge various miRNAs to enhance cell malignant behaviours in thyroid cancer cells." (PMID 36494673, 2022). "Similarly, lncRNA HOTAIR upregulates PPME1 to impact thyroid cancer cell behaviors through miR-761 competition." (PMID 35443670, 2022). "The HOTAIR expression in serum or in thyroid tissues collected via fine-needle aspiration biopsies can serve as one of useful markers to differentiate benign nodules and thyroid cancers." (PMID 36494673, 2022). "HOTAIR is upregulated in thyroid carcinoma compared with normal thyroid tissue." (PMID 35368894, 2022).
thyroid cancer (continued). "Based on these results and on the observation that MALAT1 exhibited the higher expression in tumors and that HOTAIR and PVT1 the higher increase as compared to the contra-lateral tissue, we selected MALAT1, HOTAIR, and PVT1 as potential new diagnostic markers for thyroid cancer." (PMID 33030666, 2021). "In addition, various Hox isoforms and HOTAIR also have high expression in thyroid cancer cells and tissues." (PMID 33402862, 2020). "Additionally, in vitro experiments indicated that knocking down HOTAIR can significantly inhibit the growth and invasion of thyroid cancer cells." (PMID 32596158, 2020). "Moreover, higher expression levels of plasma HOTAIR were positively correlated with worse 5-year survival rates in patients with thyroid cancer." (PMID 32596158, 2020). "Silencing HOTAIR expression inhibits thyroid cancer cell growth in vivo and in vitro." (PMID 32596158, 2020). "Additionally, knockdown of HOTAIR inhibited thyroid cancer cell growth and invasion." (PMID 40463874, 2025). "Thus, HOTAIR abundance could serve as a novel biomarker for assessing progression and malignancy in thyroid carcinomas." (PMID 40149701, 2025). "In thyroid cancer, Metastasis-Associated Lung Adenocarcinoma Transcript 1 (MALAT1) is upregulated in several subtypes such as papillary and follicular cancer and Homeobox transcript antisense RNA (HOTAIR) acts as an oncogene and correlates with metastasis and poor prognosis." (PMID 33030666, 2021). "Sedaghati summarized the dysregulated and functional LncRNAs in thyroid cancer, including 28 upregulated LncRNAs, such as ANRIL, BANCR, H19, HOTAIR, MALAT1, and NEAT1, and 22 downregulated LncRNAs, including GAS5, NAMA, PTCSC2, and PTCSC3." (PMID 37874339, 2024). "In thyroid cancer, several lncRNAs, such as MALAT1, H19, BANCR, and HOTAIR have been identified as contributing factors to tumor development, and used as novel biomarkers for early diagnosis or treatment." (PMID 34404767, 2021). "In thyroid cancer, several lncRNAs, such as MALAT1, H19, BANCR, HOTAIR have been identified as contributing factors to the development of cancer." (PMID 34404767, 2021). "However, rs7958904 may alter HOTAIR’s secondary structure (in silico CRC-related study), H19 rs2839698 is linked to higher risk in digestive system cancers, and PTCSC3 rs944289 reduces promoter activity and PTCSC3 expression in thyroid carcinoma (GWAS Catalog: GCST000335)." (PMID 41463069, 2025). "Also, HOTAIR can down-regulate miR-488-5p with upregulation of NUP205 and Bcl-2 to enhance growth, migration, and invasion of the papillary (BCPAP) thyroid cancer cell." (PMID 36494673, 2022). "Similarly, HOTAIR promotes cell viability, migration, and invasion in papillary (TPC-1) and follicular (FTC-133) thyroid cancer cells via counter-regulating miR-17-5p." (PMID 36494673, 2022). "We defined a predictive algorithm based on naïve Bayes classifier for identifying patients with thyroid cancer with accuracy of 94.12% (sensitivity 100% and specificity 91.67%) using MALAT1, HOTAIR, and PVT1 expression in FNA samples and the cytological class." (PMID 33030666, 2021).